DBI (diazepam binding inhibitor, acyl-CoA binding protein)
Description:
Binds medium- and long-chain acyl-CoA esters with very high affinity and may function as an intracellular carrier of acyl-CoA esters. It is also able to displace diazepam from the benzodiazepine (BZD) recognition site located on the GABA type A receptor. It is therefore possible that this protein also acts as a neuropeptide to modulate the action of the GABA receptor.
Synonyms: ACBP; EP; ACBD1; CCK-RP
Tractability: Small molecule: a structure with a bound ligand is known. PROTAC: ubiquitination databases record sites on it; its protein half-life has been measured.
Gene: Protein-coding gene on chromosome 2 (119,366,917 to 119,372,551, forward strand). Ensembl gene ENSG00000155368.
Subcellular location: Endoplasmic reticulum; Golgi apparatus
Pathways (Reactome):
Metabolism: Mitochondrial Fatty Acid Beta-Oxidation
Gene Ontology:
Molecular function: identical protein binding; long-chain fatty acyl-CoA binding; benzodiazepine receptor binding; fatty-acyl-CoA binding
Biological process: phosphatidylcholine acyl-chain remodeling; positive regulation of phospholipid transport; fatty acid metabolic process
Cellular component: endoplasmic reticulum; extracellular exosome; Golgi apparatus; protein-lipid complex; endoplasmic reticulum lumen
Genetic constraint (gnomAD): Loss-of-function variants: 8 observed, 7.73 expected, observed/expected ratio (o/e) 1.03, 90% interval 0.6 to 1.75. That is too few expected variants to judge how well the gene tolerates losing a copy. Missense variants: 71 observed, 78.12 expected, observed/expected ratio (o/e) 0.91, 90% interval 0.75 to 1.11. Synonymous variants: 27 observed, 28.28 expected, observed/expected ratio (o/e) 0.95, 90% interval 0.7 to 1.32.
Homologues: Orthologues: chimpanzee DBI (98% identical), macaque DBI (90% identical), pig DBI (86% identical), rabbit DBI (83% identical), dog DBI (82% identical), guinea pig DBI (82% identical), zebrafish dbi (77% identical), mouse Dbi (76% identical), rat Dbi-ps3 (72% identical), rat AABR07036498.1 (70% identical), rat Dbi (69% identical), tropical clawed frog dbi (63% identical), and 2 more. Paralogues in human: ACBD7 (62% identical), ACBD5 (48% identical), ECI2 (47% identical), ACBD4 (46% identical).
Diseases named in the same sentence as DBI in open-access papers:
DBI is named in the same sentence as 43 diseases in open-access papers, as found by Europe PMC text mining. Sharing a sentence is not in itself a finding about the gene and the disease. The quoted sentences say what the papers report.
Obesity (7 papers, 2012 to 2025). Accumulation of substantial excess body fat. "Since obesity is coupled to an inhibition of autophagy, it appears improbable that this effect may be explained by an enhanced autophagy-dependent release of ACBP/DBI protein from the intracellular space." (PMID 34308254, 2021).
liver disease (2 papers, 2024 to 2025). "Acyl coenzyme A binding protein (ACBP encoded by diazepam binding inhibitor DBI) is involved in non-malignant liver diseases." (PMID 40628264, 2025).
metabolic syndrome (2 papers, 2021 to 2025). A cluster of metabolic risk factors for CARDIOVASCULAR DISEASES and TYPE 2 DIABETES MELLITUS. "However, it is tempting to speculate that loss-of-function mutations in AR leading to complete androgen insensitivity syndrome (CAIS) cause obesity and metabolic syndrome due to the upregulation of ACBP/DBI." (PMID 40011442, 2025).
psoriasis (2 papers, 2015 to 2026). An autoimmune condition characterized by red, well-delineated plaques with silvery scales that are usually on the extensor surfaces and scalp. "All other DEGPs could be placed along a continuum, with some showing greater psoriasis specificity (e.g., DBI, GLTP, HRNR, KRT73, ELOVL7), and others showing similar expression shifts in many or most skin diseases (e.g., MX1, S100A8, S100A9, STAT1, LAP3)." (PMID 26251673, 2015). "However, given distinct functional properties of psoriasis-specific and non-specific DEGPs, it may be appropriate for such applications to assign greater emphasis to the most psoriasis-specific DEGPs, such as NCCRP1, DBI and GLTP." (PMID 26251673, 2015).
anxiety disorder (1 paper, 2018). A category of psychiatric disorders which are characterized by anxious feelings or fear often accompanied by physical symptoms associated with anxiety. "DBI gene polymorphisms are also associated with anxiety disorders." (PMID 30220890, 2018).
brain tumors (1 paper, 2022). "The identified upregulated proteins included DBI, which has been shown to be upregulated in several human brain tumors; cytochrome C, which plays an important role in apoptosis; and the NDFB3 complex, which is part of the mitochondrial membrane respiratory chain." (PMID 35216124, 2022).
Cachexia (1 paper, 2025). Severe weight loss, wasting of muscle, loss of appetite, and general debility related to a chronic disease. "Acyl-CoA Binding Protein (ACBP), also known as diazepam-binding inhibitor (DBI), is a regulator of autophagy and metabolism, and has recently been shown to increase in individuals undergoing voluntary fasting and in patients with cancer cachexia-induced malnutrition." (PMID 40867617, 2025).
cholestasis (1 paper, 2021). Impairment of the bile flow caused by obstruction within the liver, or outside the liver in the bile duct system. "CYP4A1 and DBI are involved in the PPAR signaling pathway, which is related to cholestasis." (PMID 34512777, 2021).
COVID-19 (1 paper, 2021). A disease caused by infection with severe acute respiratory syndrome coronavirus 2. "In CD14+ monocytes, HIF-1 signaling may regulate LDHA, ALDOA, TIMP1, ELOB and IFNGR2, and PPAR signaling may regulate UBC, RXRA, DBI and ACSL1 in COVID-19 patients." (PMID 33936072, 2021).
Cushing syndrome (1 paper, 2024). Cushing's syndrome (CS) encompasses a group of hormonal disorders caused by prolonged and high exposure levels to glucocorticoids that can be of either endogenous (adrenal cortex production) or exogenous (iatrogenic) origin. "The authors highlight the role of acyl coenzyme A binding protein (encoded by DBI) in Cushing’s syndrome by using six different inhibition methods and mapping the physiological effects." (PMID 39578649, 2024).
dementia (1 paper, 2015). Loss of intellectual abilities interfering with an individual's social and occupational functions. "Furthermore, additional proteins which were consistently altered in both the FLNC-, GRN- and VCP-unique datasets, e.g. GFAP, NPTN, DBI, PRDX6, MARCKS and BSN, are closely associated with cognitive function, dementia and pathological aging." (PMID 26555887, 2015).
hepatocellular carcinoma (1 paper, 2025). A malignant tumor that arises from hepatocytes. "Here, we show that DBI mRNA and circulating ACBP/DBI levels are increased in patients with hepatocellular carcinoma (HCC)." (PMID 40628264, 2025).
herpes infections (1 paper, 2013). "During herpes infections, many genes involved in metabolism like oat or fasn are under expressed, whereas others, like dbI and wnk1, are overexpressed, suggesting a disruption in host metabolic activity." (PMID 23987141, 2013).
ischemic stroke (1 paper, 2025). A stroke disorder caused by obstruction of blood flow to the brain, due to thrombotic (local blood clot formation) or embolic (due to a blood clot or other material traveling from another site) event. "Despite their known roles in cellular metabolism, the direct involvement of DBI, PGLS, GYG1, and TALDO1 in ischemic stroke remains scarce, warranting further investigation into their potential roles in stroke pathophysiology." (PMID 41342963, 2025).
mental disorder (1 paper, 2025). A disease that has its basis in the disruption of mental process. "We identified four key genes and their downstream pathways, specifically QDPR, DBI, MAX and HP genes, linking the mental disorders and susceptibility to the development of IBD." (PMID 40118833, 2025). "By integrating evidence from multi-omics perspectives, we identified four mental disorder-related genes: QDPR (Tier 1), DBI (Tier 1), MAX (Tier 3) and HP (Tier 3) as prior regulatory genes in the pathogenic pathway of IBD and its subtypes." (PMID 40118833, 2025). "We identified four mental disorder-related genes, i.e., QDPR, DBI, MAX and HP and their downstream pathways that played crucial role in the susceptibility of IBD and UC, suggesting their potential as intervention and therapeutic targets for gut-brain axis diseases in the future." (PMID 40118833, 2025).
osteoarthritis (1 paper, 2025). A noninflammatory degenerative joint disease occurring chiefly in older persons, characterized by degeneration of the articular cartilage, hypertrophy of bone at the margins and changes in the synovial membrane. "The plasma concentrations of acyl CoA binding protein (ACBP) encoded by the gene diazepam binding inhibitor (DBI) are increased in patients with severe osteoarthritis (OA)." (PMID 40082721, 2025).
overnutrition (1 paper, 2021). An imbalanced nutritional status resulting from excessive intake of nutrients. "In mice, the plasma concentrations of the appetite-stimulatory and autophagy-inhibitory factor acyl-coenzyme A binding protein (ACBP, also called diazepam-binding inhibitor, DBI) acutely increase in response to starvation, but also do so upon chronic overnutrition leading to obesity." (PMID 34108446, 2021).
schizophrenia (1 paper, 2018). A major psychotic disorder characterized by abnormalities in the perception or expression of reality. "Multiple missense mutations have been reported in the DBI gene in schizophrenia." (PMID 30220890, 2018).
tumor (5 papers, 2021 to 2025). "On the other hand, in domain 4, we observed upregulation of KRT8, AQP3, KLHDC7B and CDH1, which tend to exhibit stronger tumor progression and metastasis, and high expression of genes NUPR1 and DBI associated with chemotherapy resistance." (PMID 36250636, 2022). "ACBP1/DBI silencing induces cell senescence, reduces cell proliferation, delays tumor initiation and prolongs survival in in vivo model." (PMID 34320944, 2021). "TUBA1A, DBI, and TUBB are up-regulated in tumor cells and down-regulated in periphery cells, and these are marker genes for the neoplastic cluster." (PMID 35327982, 2022). "Collectively, these findings suggest that DBI may act as a metabolic regulator that differentially modulates immune cell function within the TME, with potential implications for metabolic reprogramming strategies to boost anti-tumor immunity." (PMID 40426943, 2025).
cancer (4 papers, 2024 to 2025). A tumor composed of atypical neoplastic, often pleomorphic cells that invade other tissues. "Mouse experimentation revealed that genetic or antibody-mediated DBI/ACBP inhibition can delay the development or progression of cancers." (PMID 39419485, 2024).
infection (1 paper, 2008). The state of being infected such as from the introduction of a foreign agent such as serum, vaccine, antigenic substance or organism. "Transcripts of caspase 3 (CASP3), Acyl coenzyme A-binding protein (DBI), death inducer-obliterator-1 (DIDO1) and Bcl2-related protein A1 (BCL2A1), are pro-apoptotic proteins or induced by apoptosis, and were down-modulated upon infection." (PMID 18495030, 2008).
DBI also shares sentences with these, for which no sentence is quoted: cardiovascular disease (3 papers); glioblastoma (3); glioma (3); Alzheimer disease (1); atherosclerosis (1); autism spectrum disorder (1); cardiomyopathy (1); complete androgen insensitivity syndrome (1); diabetes (1); gestational diabetes mellitus (1); hypothyroidism (1); Insulin resistance (1); liver cancer (1); major depressive disorder (1); malnutrition (1); non-small cell lung carcinoma (1); osteoporosis (1); panic attacks (1); periodontitis (1); peroxisomal disorders (1); Sepsis (1); Stroke (1).